MUC17 (mucin 17, cell surface associated)
Description:
Probably plays a role in maintaining homeostasis on mucosal surfaces.
Synonyms: MUC-17; MUC-3; MUC3
Tractability: Antibody: UniProt places it where antibodies can reach, with high confidence; its Gene Ontology location is reachable by antibodies, with high confidence; UniProt predicts a signal peptide or a membrane-spanning region.
Gene: Protein-coding gene on chromosome 7 (101,020,072 to 101,058,859, forward strand). Ensembl gene ENSG00000169876.
Subcellular location: Cell membrane (Isoform 1); Secreted (Isoform 2); Cell membrane
Pathways (Reactome):
Disease: Defective C1GALT1C1 causes TNPS; Defective GALNT12 causes CRCS1; Defective GALNT3 causes HFTC
Metabolism of proteins: O-linked glycosylation of mucins; Termination of O-glycan biosynthesis
Immune System: Dectin-2 family
Gene Ontology:
Molecular function: extracellular matrix constituent, lubricant activity; PDZ domain binding; protein binding
Biological process: cellular homeostasis
Cellular component: apical plasma membrane; external side of plasma membrane; extracellular matrix; Golgi lumen; plasma membrane; extracellular region
Genetic constraint (gnomAD): Loss-of-function variants: 190 observed, 175.77 expected, observed/expected ratio (o/e) 1.08, 90% interval 0.96 to 1.22. The synonymous counts are far from expectation, so gnomAD's model fits this gene poorly and the ratio says little. Missense variants: 6,397 observed, 5,426.4 expected, observed/expected ratio (o/e) 1.18, 90% interval 1.15 to 1.2. Synonymous variants: 2,316 observed, 1,977.3 expected, observed/expected ratio (o/e) 1.17, 90% interval 1.13 to 1.21.
Homologues: Orthologues: mouse Muc17 (24% identical). Paralogues in human: MUC3A (18% identical), MUC13 (2% identical).
Diseases named in the same sentence as MUC17 in open-access papers:
MUC17 is named in the same sentence as 53 diseases in open-access papers, as found by Europe PMC text mining. Sharing a sentence is not in itself a finding about the gene and the disease. The quoted sentences say what the papers report.
gastric cancer (9 papers, 2011 to 2025). A primary or metastatic malignant neoplasm involving the stomach. "Particularly in gastric-cancer tissues, MUC17 is overexpressed in approximately 50% of the gastric-cancer cases." (PMID 35628495, 2022). "It induces the activation and proliferation of CD3+ T-cells and activates T-cell-mediated tumor-cell lysis in MUC17-positive gastric cancer." (PMID 35628495, 2022). "One gene (MUC17) that is only detected based on GCPan was also related to gastric cancer." (PMID 39870503, 2025). "MUC17 was detected only based on GCPan and was related to gastric cancers." (PMID 39870503, 2025). "Thus, MUC17 is a compelling target in gastric cancer because of its prevalent expression on tumor cells compared with its low, relatively restricted expression in normal tissues." (PMID 35628495, 2022). "MUC17 is reported to be a tumor suppressor in gastric cancer." (PMID 34885197, 2021). "Analysis of The Cancer Genome Atlas database indicated that mucin-17 (MUC17) was more highly expressed in gastric cancer (GC) specimens, with favourable prognosis for patients." (PMID 31262330, 2019).
breast carcinoma (5 papers, 2017 to 2024). "Given the role of MUC17 mutations in chemoresistance and in early onset breast cancer, its high prevalence and exclusive occurrence in the Kenyan samples that are prone to early onset of breast cancer should be investigated further." (PMID 39723380, 2024). "Second, compared to conventional breast cancer, somatic mutations in MUC17, FLG and NEBL were of much higher prevalence among EOBC patients." (PMID 32731431, 2020). "A high mutation frequency for MUC17 and TTN have recently been reported as an unexpected finding in a study of early onset breast cancer (EOBC) in Taiwanese women." (PMID 39723380, 2024). "Silencing the expression of MUC17 significantly increases the chemotherapy sensitivity in breast cancer." (PMID 35847355, 2022). "Despite MUC17 appearing to be turned off in multiple breast cancer histological subtypes, several cohorts suffer from weak sample size." (PMID 28978023, 2017). "Thus, the role of MUC17 and TTN should further be investigated on how mutations in them may relate to early onset of breast cancer in Kenyan patients." (PMID 39723380, 2024).
colon carcinoma (5 papers, 2012 to 2023). "Additionally, the human colon cancer cell line LS174T has consistently been shown to express MUC17." (PMID 36900282, 2023). "Robust markers of metaplasia in our study included cathepsin E (CTSE), which has been associated with gastric and colon cancers and previously shown to be upregulated in patients with BAR and EAC, as well as the anion/bicarbonate channel CFTR and PDZ-domain-containing mucins MUC17, MUC3A, and MUC12." (PMID 34412659, 2021). "The MUC17 expression rate in colon cancer is unknown, but is lower than that in normal epithelium." (PMID 25551773, 2014). "In addition, it also has been reported that stable transfection of small hairpin RNA targeting endogenous MUC17 in colon cancer LS174T cells resulted in reduced cell aggregation, reduced cell–cell adherence and migration, and increased susceptibility to apoptosis." (PMID 22970168, 2012).
glioma (5 papers, 2019 to 2025). A benign or malignant brain and spinal cord tumor that arises from glial cells (astrocytes, oligodendrocytes, ependymal cells). "Mutations in MUC17 are known to be associated with poor prognosis in glioma." (PMID 39636205, 2024). "MUC17, encoded a membrane‐bound mucin, played an antiadhesive role in cancer cells that lose their apical/basal polarization and has been reported as a potential negative prognostic biomarker for several solid tumors including breast, glioma, gastric, colon, and biliary tract cancers." (PMID 40727251, 2025). "The mutation of HMCN1 and MUC17 may induce the increased cytolytic activity of glioma." (PMID 31428092, 2019). "Specific mucins that have now been implicated in glioma include MUC1, MUC4, MUC15, MUC16, MUC17, MUC18 and MUC21." (PMID 39767713, 2024). "MUC17 may influence chemoresistance and has recently been reported as a driver gene in adult gliomas." (PMID 39723380, 2024). "While MUC1, MUC4, MUC15, MUC16, MUC17, and MUC21 are all potential candidate biomarkers for glioma, the extensive research on MUC1 and the current clinical application of MUC16 in ovarian cancer highlights their promise as therapeutics for glioma." (PMID 39767713, 2024).
colitis (4 papers, 2014 to 2024). Inflammation of the colon. "Muc17 deletion in mice rendered the small intestine particularly prone to atypical bacterial infection while maintaining resistance to colitis." (PMID 39699961, 2024). "Mouse models of colitis exhibit augmented healing after treatment with truncated recombinant MUC17, suggesting that MUC17 can play a protective role during chronic inflammation." (PMID 31387973, 2019). "Muc17 is dispensable for protection against chemically induced colitis." (PMID 39699961, 2024). "The VNN1 finding, together with increased REG4 and MUC17, that are also increased during colitis, suggests that the development of SSA/Ps may at least in part involve inflammatory processes." (PMID 24533081, 2014). "That Muc17ΔIEC mice are only slightly more susceptible to acute DSS challenge, a model for colonic inflammation (colitis), suggests that Muc17 does not play a critical role in the colonic defense system." (PMID 39699961, 2024). "The late onset of moderate inflammation in the absence of Muc17 contrasted acute induction of severe colitis in C3GnT–/–, Vamp8–/–, and Tgm3–/– mice with defects in Muc2 glycosylation, secretion, and cross-linking." (PMID 39699961, 2024).
pancreatic cancer (4 papers, 2010 to 2019). "Secondly, we selected MUC17 (Mucin-17), which is a type of mucin overexpressed in pancreatic tumor cell lines and tumor tissues compared with the normal pancreas." (PMID 31443431, 2019). "Our results show that MUC17 is induced by HIF1α mediating hypoxic response, and the specific DNA methylation determines the hypoxic inducibility of MUC17 in pancreatic cancer cells." (PMID 22970168, 2012). "In this context, we recently reported that DNA hypomethylation is a key factor for MUC17 expression in pancreatic cancer." (PMID 22970168, 2012). "The level of MUC17 mRNA was strongly correlated to the hypomethylation status of HRE within the MUC17 promoter in pancreatic cancer." (PMID 22970168, 2012). "Taken together, our study demonstrates for the first time that MUC17 expression is enhanced by the HIF1α-mediated hypoxic response and that DNA methylation of HRE is a key determinant of the hypoxic inducibility of MUC17 in pancreatic cancer." (PMID 22970168, 2012). "To examine the effect of hypoxic exposure on MUC17 expression, we cultured human pancreatic cancer cells AsPC1 under hypoxic culture conditions (1% O2) for 2 days." (PMID 22970168, 2012). "MUC17 was also shown to be overexpressed in pancreatic tumor cell lines and tumor tissues compared with the normal pancreas." (PMID 24281201, 2010). "Our data revealed that MUC17 was significantly induced by hypoxic stimulation through a hypoxia-inducible factor 1α (HIF1α)-dependent pathway in some pancreatic cancer cells (e.g., AsPC1), whereas other pancreatic cancer cells (e.g., BxPC3) exhibited little response to hypoxia." (PMID 22970168, 2012). "Furthermore, to evaluate the biological significance of HRE methylation in MUC17 expression, we examined MUC17 expression and methylation status in normal and pancreatic tumor tissues from patients with PDACs by RT-PCR and MSP, respectively." (PMID 22970168, 2012). "Moreover, the use of four cell lines with different MUC17 hypoxic inducibilities allowed us to propose a model for the epigenetic regulation of MUC17 in pancreatic cancer." (PMID 22970168, 2012). "Although further studies are needed to elucidate the other factors involved in MUC17 expression, this could explain why MUC17 is overexpressed in pancreatic cancer." (PMID 22970168, 2012). "In the present study, we investigated the hypoxic regulation of MUC17 in pancreatic cancer cells." (PMID 22970168, 2012). "Furthermore, we evaluated whether the hypoxic induction of MUC17 is a universal event in pancreatic cancer cells." (PMID 22970168, 2012). "Only a strong enhancer was found in the MUC17 upstream region with a significant promoter activity in AsPC-1, and HPAF pancreatic cancer cell lines." (PMID 24281201, 2010). "MUC17 expression is related to tumor progression in pancreatic cancer, but was not related to clinicopathological factors or survival in appendiceal carcinoma." (PMID 25551773, 2014). "Taken together, these findings suggested that the HIF1α-mediated hypoxic signal pathway contributes to MUC17 expression, and DNA methylation of HRE could be a determinant of the hypoxic inducibility of MUC17 in pancreatic cancer cells." (PMID 22970168, 2012).
ulcerative colitis (4 papers, 2014 to 2024). An inflammatory bowel disease involving the mucosal surface of the large intestine and rectum. "Mucins including MUC4, MUC12 and MUC17 are important for intestinal integrity and have previously been associated with both ulcerative colitis (UC) and Crohn's disease (CD)." (PMID 24988487, 2014). "MUC17 is downregulated in inflammatory states such as ulcerative colitis and ischemic colitis." (PMID 36900282, 2023). "Changes in glycocalyx composition could also be expected, as RNAseq analysis of mucosal biopsies from ulcerative colitis patients in remission show an increased expression of MUC17 compared to those in active state and controls." (PMID 35805133, 2022).
lung adenocarcinoma (3 papers, 2016 to 2022). A carcinoma that arises from the lung and is characterized by the presence of malignant glandular epithelial cells. "The C3 immune subtype of lung adenocarcinoma exhibited longer survival, whereas the C1 subtype was associated with a higher mutation rate of MUC17 and FLG genes compared with other subtypes." (PMID 35354459, 2022). "Lung squamous cell carcinoma (LUSC) and lung adenocarcinoma (LUAD) share MUC16 and MUC17 mutations at a similar rate between the histological subtypes." (PMID 28978023, 2017). "Interestingly, among them, MUC17 was reported to be a potential oncogene specific for lung adenocarcinoma." (PMID 27036025, 2016).
adenoma (2 papers, 2014 to 2023). A neoplasm arising from the epithelium. "Marked increased expression of MUC17, the cell junction protein genes VSIG1 and GJB5, and the antiapoptotic gene REG4 were found in SSA/Ps, relative to controls and adenomas, were verified by qPCR analysis of additional SSA/Ps (n = 21) and adenomas (n = 10)." (PMID 24533081, 2014).
biliary tract cancer (2 papers, 2022 to 2025).
endometriosis (2 papers, 2015 to 2017). The growth of functional endometrial tissue in anatomic sites outside the uterine body. "In this study, we analyzed and found the association between MUC17 polymorphisms and endometriosis, endometriosis-related infertility and CA125 in a Taiwanese population." (PMID 26285705, 2015). "This study was focused on the potential impact of genetic variations in MUC17 on endometriosis development and associated clinical features." (PMID 26285705, 2015). "To investigate the possible link with endometriosis, we studied the association of MUC17 genetic variants with the ovarian cancer biomarker CA125 and the related infertility." (PMID 26285705, 2015). "Genotyping revealed that the A allele at rs10953316 in MUC17 was a protective genetic factor in endometriosis development (p = 0.008; OR = 0.53; 95 % CI: 0.36-0.79)." (PMID 26285705, 2015). "Because endometriosis is considered one of the factors that cause infertility, we next studied the relationship between MUC17 SNPs and infertility." (PMID 26285705, 2015). "MUC17 polymorphisms are involved in endometriosis development and the associated infertility in the Taiwanese population." (PMID 26285705, 2015). "In this study, we showed molecular evidence that the A allele of rs10953316 in MUC17 may function as a protective factor in endometriosis development." (PMID 26285705, 2015). "Additionally, gene expression profiling has confirmed MUC17 to be overexpressed in mucinous ovarian carcinoma; however, its associated risk for endometriosis remains unclear." (PMID 26285705, 2015). "Recently, it has been suggested that CYP17, VDR, MUC17, COX-2, WNT4, E-cadherin, CYP19, CYP17, TYK2, NFKB1, and MUC2 gene variants also contributed to endometriosis-related infertility." (PMID 28405865, 2017). "The detailed regulatory mechanisms regarding how MUC17 functions and collaborates with its binding miRNAs in promoting endometriosis development remain to be elucidated." (PMID 26285705, 2015). "Because mRNA structural change could be a hindrance to its stability and translation efficiency, we performed immunohistochemistry on endometriosis tissues to see whether such variation can influence the total amount of MUC17." (PMID 26285705, 2015). "Although several lines of evidence support a potent role of MUC17 in tumor development, its role in endometriosis remains unclear." (PMID 26285705, 2015).
esophageal cancer (2 papers, 2018 to 2025). A primary or metastatic malignant neoplasm involving the esophagus. "Moreover, Cox2 is well known to be involved in CRC carcinogenesis and has been suggested to act by inducing Muc5B and Muc17 secreting cells in the pathogenesis of esophageal cancer." (PMID 29547645, 2018).
inflammatory bowel disease (2 papers, 2018 to 2019). A spectrum of small and large bowel inflammatory diseases of unknown etiology. "Inflammatory bowel disease (IBD) is associated with a dysfunctional mucus barrier and abnormalities in gene expression of certain secreted and transmembrane mucins, including MUC17." (PMID 31387973, 2019).
pancreatic ductal adenocarcinoma (2 papers, 2012 to 2022). An infiltrating adenocarcinoma that arises from the epithelial cells of the pancreas. "A total of 63% of pancreatic ductal adenocarcinoma carried mucin gene alteration events, and the frequency of MUC17 is 15%." (PMID 35847355, 2022). "Recent studies have demonstrated that the aberrant overexpression of MUC17 is correlated with the malignant potential of pancreatic ductal adenocarcinomas (PDACs); however, the exact regulatory mechanism of MUC17 expression has yet to be identified." (PMID 22970168, 2012).
colorectal adenocarcinoma (1 paper, 2025). The most common type of colorectal carcinoma. "To identify proteins responsible for the apical targeting of MUC17, we turned to the Caco-2 colorectal adenocarcinoma cell line." (PMID 39661054, 2025).
colorectal cancer (1 paper, 2022). A primary or metastatic malignant neoplasm that affects the colon or rectum.
cystic teratomas of the ovary (1 paper, 2022). "Among the 15 prevalent mutated genes, 8 with different variants in exons with changes in protein coding are important for the development of mature cystic teratomas of the ovary: FLG, MUC17, MUC5B, RP1L1, NBPF1, SLC29A3, SGK223, and FAM186A." (PMID 36289533, 2022).
E. coli infection (1 paper, 2019). "MUC17 has been suggested to play a role in cell restitution and protection of epithelial cells from E. coli infection." (PMID 31387973, 2019).
endometrioid endometrial adenocarcinoma (1 paper, 2017). "Uterine corpus endometrioid endometrial adenocarcinoma (UEC) appears to acquire more mutations in multiple mucins, including MUC5B and MUC17, which becomes very prominent in stage III." (PMID 28978023, 2017).
Intellectual disability (1 paper, 2019). "MUC17 is one of the over 100 genes recently reported to be included in the interstitial deletion of the 7q22.1 syndrome, which is characterized by structural brain abnormalities and intellectual disability." (PMID 31620175, 2019).
laryngeal carcinoma (1 paper, 2025). Carcinoma that arises from the laryngeal epithelium. "We anticipate that by targeting mucin‐overexpressing laryngeal cancer cells, the chitosan‐coated liposomes will electrostatically bind to transmembrane mucins like MUC1, MUC4, MUC17 and thus enhance the drug intake and retention process." (PMID 40385549, 2025).
lung carcinoma (1 paper, 2023). "In summary, our study reveals that long-term gefitinib/osimertinib exposure enhances genome-wide methylation and promotes drug resistance in lung cancer cells through UHRF1/DNMT1-mediated epigenetic silencing of MUC17." (PMID 36778111, 2023). "Here, we demonstrated a more complicated epigenetic regulation of MUC17 in lung cancer." (PMID 36778111, 2023).
lung malignant tumors (1 paper, 2023). "Therefore, MUC17 plays an inhibitory role in lung malignant tumors and is a biomarker for monitoring EGFR-TKIs resistance." (PMID 36778111, 2023).
melanoma (1 paper, 2023). A malignant, usually aggressive tumor composed of atypical, neoplastic melanocytes. "It is of note that in these three cases AHNAK2, MUC4, MUC16, and MUC17 mutations were found, which were previously reported to be involved in antitumoral immune mechanisms of melanoma." (PMID 36980598, 2023).
mucinous ovarian carcinoma (1 paper, 2015). An invasive malignant neoplasm that arises from the ovary and is characterized by the presence of malignant epithelial cells that contain intracytoplasmic mucin and may resemble the epithelial cells of the endocervix or gastrointestinal tract. "In this study, we investigated the association between genetic variations of MUC17 (A.K.A. MUC3) and endometriosis development based on the finding of gene expressing profiling in mucinous ovarian carcinoma (MOC), which likely arises from endometriosis." (PMID 26285705, 2015).